ADORA1 (adenosine A1 receptor)
Description:
Receptor for adenosine. The activity of this receptor is mediated by G proteins such as GNAI2 which inhibit adenylyl cyclase.
Synonyms: RDC7
Tractability: Small molecule: an approved drug acts on it; a structure with a bound ligand is known; a high-quality ligand is known; it belongs to a druggable protein family. Antibody: UniProt places it where antibodies can reach, with high confidence; its Gene Ontology location is reachable by antibodies, with high confidence; UniProt predicts a signal peptide or a membrane-spanning region; the Human Protein Atlas places it where antibodies can reach. PROTAC: a small molecule that binds it is known.
Target class: Family A G protein-coupled receptor; Membrane receptor; Small molecule receptor (family A GPCR); Adenosine receptor; Nucleotide-like receptor (family A GPCR)
Chemical probes: CHEMBL3613119, GR79236, LUF5981, PD003180, TCPA (high quality)
Safety:
Unwanted effects reported when the protein is acted on. In parentheses: how it was acted on, where the effect was seen, and who reports it.
atrioventricular block (activation, acute dosing; nervous system, renal, cardiovascular; source: Lynch et al. (2017))
bradycardia (activation; cardiovascular system, nervous system, renal; source: Urban et al. (2012))
bronchoconstriction (activation; cardiovascular system, nervous system, renal; source: Urban et al. (2012))
cardiac arrhythmia (activation, acute dosing; nervous system, renal, cardiovascular; source: Lynch et al. (2017))
cardioprotection (activation; cardiovascular system, nervous system, renal; source: Urban et al. (2012))
convulsions (inhibition, acute dosing; nervous system, renal, cardiovascular; source: Lynch et al. (2017))
death (activation, acute dosing; nervous system, renal, cardiovascular; source: Lynch et al. (2017))
decreased blood pressure (activation, acute dosing; nervous system, renal, cardiovascular; source: Lynch et al. (2017))
decreased heart rate (activation, acute dosing; nervous system, renal, cardiovascular; source: Lynch et al. (2017))
decreased pain (activation, acute dosing; nervous system, renal, cardiovascular; source: Lynch et al. (2017))
diuresis (inhibition; cardiovascular system, nervous system, renal; source: Urban et al. (2012))
heart failure (activation, acute dosing; nervous system, renal, cardiovascular; source: Lynch et al. (2017))
increased urinary sodium excretion (inhibition, acute dosing; nervous system, renal, cardiovascular; source: Lynch et al. (2017))
increased urine excretion (inhibition, acute dosing; nervous system, renal, cardiovascular; source: Lynch et al. (2017))
induction of sleep (activation; cardiovascular system, nervous system, renal; source: Urban et al. (2012))
natriuresis (inhibition; cardiovascular system, nervous system, renal; source: Urban et al. (2012))
vasoconstriction (activation; cardiovascular system, nervous system, renal; source: Urban et al. (2012))
vasodilation (inhibition; cardiovascular system, nervous system, renal; source: Urban et al. (2012))
aspirin-intolerant asthma (source: ClinPGx)
Gene: Protein-coding gene on chromosome 1 (203,090,654 to 203,167,407, forward strand). Ensembl gene ENSG00000163485.
Subcellular location: Cell membrane
Subcellular location (Human Protein Atlas): Plasma membrane; Primary cilium
Pathways (Reactome):
Signal Transduction: Adenosine P1 receptors; G alpha (i) signalling events
Gene Ontology:
Molecular function: protein binding; G protein-coupled adenosine receptor activity; G protein-coupled receptor binding; G protein-coupled receptor activity; G-protein beta/gamma-subunit complex binding; heat shock protein binding; heterotrimeric G-protein binding; protein heterodimerization activity; protein-containing complex binding; purine nucleoside binding
Biological process: response to purine-containing compound; apoptotic signaling pathway; cell-cell signaling; G protein-coupled purinergic nucleotide receptor signaling pathway; G protein-coupled receptor signaling pathway; inflammatory response; nervous system development; phagocytosis; signal transduction; adenylate cyclase-inhibiting G protein-coupled receptor signaling pathway; cognition; detection of temperature stimulus involved in sensory perception of pain; epidermal growth factor receptor signaling pathway; excitatory postsynaptic potential; fatty acid homeostasis; G protein-coupled adenosine receptor signaling pathway; lipid catabolic process; negative regulation of acute inflammatory response; negative regulation of apoptotic process; negative regulation of blood pressure; negative regulation of cell population proliferation; negative regulation of circadian sleep/wake cycle, non-REM sleep; negative regulation of circadian sleep/wake cycle, sleep; negative regulation of glutamate secretion; negative regulation of hormone secretion; and 26 more
Cellular component: plasma membrane; dendrite; synapse; asymmetric synapse; axolemma; basolateral plasma membrane; calyx of Held; cell body; dendritic spine; intracellular protein-containing complex; membrane; neuronal cell body; postsynaptic membrane; presynaptic active zone; presynaptic membrane; terminal bouton
Genetic constraint (gnomAD): Loss-of-function variants: 6 observed, 19.82 expected, observed/expected ratio (o/e) 0.3, 90% interval 0.17 to 0.6. The upper end of that interval is the gene's LOEUF score, 0.6, which puts it in group 2 of 6, group 1 being the genes least tolerant of losing a copy. Missense variants: 302 observed, 450.2 expected, observed/expected ratio (o/e) 0.67, 90% interval 0.61 to 0.74. Synonymous variants: 194 observed, 195.9 expected, observed/expected ratio (o/e) 0.99, 90% interval 0.88 to 1.12.
Homologues: Orthologues: chimpanzee ADORA1 (99% identical), macaque ADORA1 (99% identical), guinea pig ADORA1 (95% identical), mouse Adora1 (95% identical), rat Adora1 (95% identical), dog ADORA1 (94% identical), pig ADORA1 (94% identical), rabbit ADORA1 (94% identical), tropical clawed frog adora1 (69% identical), zebrafish adora1b (66% identical), zebrafish adora1a (49% identical), Drosophila melanogaster AdoR (34% identical). Paralogues in human: ADORA2A (49% identical), ADORA3 (48% identical), ADORA2B (46% identical).
Diseases named in the same sentence as ADORA1 in open-access papers:
ADORA1 is named in the same sentence as 108 diseases in open-access papers, as found by Europe PMC text mining. Sharing a sentence is not in itself a finding about the gene and the disease. The quoted sentences say what the papers report.
breast carcinoma (13 papers, 2010 to 2025). "In the context of cancer, several studies have been published indicating that overexpression of Adora1 (adenosine A1 receptor) promotes the malignant progression of colorectal, renal, and breast cancers, as well as glioblastomas and leukemias." (PMID 41346607, 2025). "The adenosine A1 receptor (ADORA1), which functions as a receptor for adenosine, has been documented to exhibit pro-tumor growth effects in breast carcinoma, renal cancer, and hepatocellular carcinoma." (PMID 40376586, 2025). "The adenosine A1 receptor plays multiple roles in the tumour microenvironment, particularly in breast cancer and other tumours." (PMID 40417221, 2025). "ADORA1 is involved in promoting tumor growth through bone marrow-derived suppressor cells and has been reported to support tumor growth outcomes in colorectal adenocarcinoma, human leukemia Jurkat cells, breast cancer and kidney cancer." (PMID 36557693, 2022). "Previous reports pointed out that ADORA1 antagonists could effectively reduce breast cancer cell line Mcf-7 cell proliferation." (PMID 34093805, 2021). "Conversely, ADORA1 was reported to promote the growth and survival of 786-O and ACHN kidney cancer cells, or MDA-MB-468 breast cancer cells." (PMID 34681900, 2021). "ADORA1 was shown to suppress proliferation and induce apoptosis in CW2 colon cancer and MCF-7 breast cancer cells." (PMID 34681900, 2021). "In the breast cancer MCF-7 cell line, the silencing of the ADORA1 gene decreases the endogenous estrogen receptor-α (ER-α) levels and causes a decline in cell proliferation." (PMID 26185765, 2015). "The most significant ones include TFF1, CCND1, IGFBP4, C3, ADORA1, GREB1, and MYC, which have been shown by candidate gene analysis to be estrogen regulated genes in breast cancer cell lines." (PMID 21878096, 2011). "Previous studies have shown that the ADIPOR1, ADORA1, BTG2 and CD46 genes differ significantly between long-term survivors of breast cancer and deceased patients, both in levels of gene expression and DNA copy numbers." (PMID 20553615, 2010). "Based on their involvement in breast cancer and the availability of commercial antibodies, the ADIPOR1, ADORA1, BTG2 and CD46 genes were selected among the 27 previously identified genes to further investigate the association of protein expression levels to overall patient survival." (PMID 20553615, 2010).
Anxiety (11 papers, 2011 to 2025). Intense feelings of nervousness, tension, or panic often arise in response to interpersonal stresses. "γ‐Aminobutyric acid (C00334) and oxytocin (Oxt), which are upstream molecules of the adenosine A1 receptor, have been shown to have significant inhibitory effects on anxiety and depression." (PMID 40735940, 2025). "However, the time spent in the central area, a parameter often used to assess depression/anxiety of mice, was heavily reduced in both groups, though the Adora1 cKO mice showed a tendency of increasing the time." (PMID 39068155, 2024). "Astrocyte activation mediated by adenosine A1 receptors (ADORA1) has been shown to disrupt memory consolidation and decrease contextual memory but did not cue fear memory which was accompanied by reduced fear-related anxiety behavior." (PMID 37363320, 2023). "Compounds such as acetylshikonin and 2-methyl-n-butyrylshikonin regulate neuroactive ligand-receptor interaction pathways through targets such as recombinant adenosine a1 receptor (ADORA1) and adenosine a2a receptor (ADORA2A), allowing exertion of anti-anxiety effects." (PMID 37169837, 2023). "Thus, we found that non-OCD anxiety disorders were related to variants of the two studied genes: rs2228079 of ADORA1 (not reaching significance) and rs5751876 of ADORA2A (significantly), which is not in line with earlier reports considering anxiety symptoms as secondary to GTS." (PMID 26317759, 2015).
depression (11 papers, 2015 to 2025). "Another target gene that we identified in the present study was ADORA1, which regulates various biological functions, including the mechanisms underlying sleep, and psychiatric disorders including depression." (PMID 36009493, 2022). "Tramadol, a drug undergoing phase IV clinical trials for depression, was discovered to target ADORA1 in the present study." (PMID 36009493, 2022). "In this context, the adenosine A1 receptor is considered to be a promising target for protective or therapeutic treatment in depressive disorders." (PMID 33015153, 2020). "The changes in Adora1, Slc6a15, and Comt expression may result in changes in the function of encoded proteins and subsequent alterations within adenosine, glutamatergic, and monoaminergic systems, all of which are critically involved in depression pathophysiology and treatment." (PMID 29882086, 2018). "Additionally, another study observed the effects of co-administering DPCPX (a selective antagonist of the adenosine A1 receptor) and magnesium on a depression model in mice and found that MSRA has the ability to repair various oxidatively damaged proteins and prevent irreversible damage." (PMID 40429617, 2025). "The genotype GG of ADORA1 rs2228079 (recessive model) was significantly more frequent in patients with OCD/OCB (OR 2.86, 95% CI: 1.14–7.21, p = 0.021) and depression (OR 2.94, 95% CI: 1.06–8.13, p = 0.032) than in patients without these co-morbidities." (PMID 26317759, 2015). "In our study we have evaluated the expression of the selected genes, which may play a role in the pathophysiology and treatment of depression or the mechanism of DPCPX and istradefylline action (i.e., Adora1, Slc6a15, Comt)." (PMID 33673282, 2021). "The GG genotype of ADORA1 rs2228079 was found significantly more frequently in patients with OCD/OCB, depression and, at borderline significance, with non-OCD anxiety disorder." (PMID 26317759, 2015).
epilepsy (10 papers, 2009 to 2024). A brain disorder characterized by episodes of abnormally increased neuronal discharge resulting in transient episodes of sensory or motor neurological dysfunction, or psychic dysfunction. "So, based on the physiological roles of adenosine A1 receptor in the brain, adenosine A1 receptor may be associated with the pathogenesis of epilepsy." (PMID 28415676, 2017). "Increased adenosine A1 receptor activity can enhance neuronal survival, supporting it as a therapeutic target for epilepsy and stroke." (PMID 39338322, 2024). "Histopathologic and biochemical analyses of surgical resections of patients with epilepsy showed a decrease in the gene expression of ADORA1, suggesting that this decrease contributes to chronic epilepsy in humans." (PMID 33551767, 2020). "More importantly, systemic application of the adenosine A1 receptor agonist 2-chloro-N6-cyclopentyladenosine (CCPA) suppressed epileptic discharges in a mouse model of drug-resistant epilepsy." (PMID 23825618, 2013). "The parallels between ketogenic diets and adenosine A1 receptor activation include their efficacy in pharmocoresistant epilepsy, and neuronal inhibition via anticonvulsants appears to be one mechanism for alleviating at least a subset of neuropathic pain." (PMID 20190967, 2009). "At the same time, NBTI mimics adenosine to attenuate the epileptiform discharge through adenosine A1 receptor, which might provide a novel therapeutic approach toward the control of epilepsy." (PMID 28415676, 2017). "Given that the anticonvulsant activity of adenosine is primarily mediated though the adenosine A1 receptor, adenosine receptor agonists may hold promise for the development of epilepsy drugs." (PMID 23825618, 2013). "Devices that promote local delivery of adenosine would overcome toxicity of adenosine kinase inhibitors, as well as systemic side effects of adenosine A1 receptor agonists, and may prove useful for idiopatic pain control in a way similar to that proposed for epilepsy control." (PMID 20190960, 2009). "Furthermore, dysregulation in ADORA1/ADORA2A expression was associated with glioma development, and a low level of ADORA1/ADORA2A expression could increase the susceptibility of tumor-associated epilepsy." (PMID 33262686, 2020).
melanoma (10 papers, 2015 to 2025). A malignant, usually aggressive tumor composed of atypical, neoplastic melanocytes. "Moreover, evidence from studies on melanoma and lung cancer demonstrates that ADORA1 deficiency combined with PD-1 mAb treatment supports our perspective." (PMID 40376586, 2025). "The combination of PD-1 and ADORA1 antibodies enhanced the treatment efficacy in melanoma and NSCLC mouse models." (PMID 36290882, 2022). "Retrospective analysis showed that melanoma patients bearing low ADORA1, high ATF3 or high PD-L1 in their tumor tissues had higher response rates to Anti-PD-1 monoclonal antibody and better prognosis." (PMID 33344447, 2020). "Moreover, recent studies show that the knockdown of ADORA1 in the human melanoma cell lines significantly suppresses cell proliferation, and this suppression leads to an antitumor effect." (PMID 37286613, 2023). "In melanoma and NSCLC cells, adenosine A1 receptor (ADORA1) inhibition promotes PD-L1 gene expression through ATF3 binding to the PD-L1 promoter directly." (PMID 35907881, 2022). "It was found that inhibition of adenosine A1 receptor, ADORA1, can upregulate the expression of PD-L1 in melanoma cells, leading to CD8+ T cell depletion and tumor immune evasion." (PMID 33344447, 2020).
asthma (8 papers, 2017 to 2023). "Among the target identified, the roles of HMGCR and ADORA1 as implicated in asthma are supported by clinical and preclinical evidence." (PMID 35052792, 2022). "The significant SNPs within loci were aligned with known asthma-susceptibility genes (e.g., ADORA1, MUC16)." (PMID 36818476, 2022). "We found increased predicted ADORA1 expression significantly associated with increased asthma risk in 4/5 MESA models tested." (PMID 30096133, 2018). "Furthermore, the significant SNPs within two loci were aligned with known asthma-susceptibility genes (e.g., ADORA1, MUC16)." (PMID 36818476, 2022). "ADORA1 has also been implicated in asthma susceptibility by GWAS and functional studies." (PMID 35386996, 2021). "Additionally, a purinergic receptor (ADORA1) has been previously implicated in asthma susceptibility by genome wide association studies (GWAS) and by functional studies, thereby further supporting the potential for purinergic receptors as therapeutic targets for asthma." (PMID 35386996, 2021). "The exact mechanisms underlying the observed relationship of genetic loci and metabolites—e.g., genes within chromosome 1q32 (e.g., ADORA1, PPFIA4) and sphingomyelin (d17:1/16:0, d18:1/15:0, d16:1/17:0)—with asthma risk warrant further clarification." (PMID 36818476, 2022). "But it is possible that rs6683383:A has the opposite effect on ADORA1 expression in other tissues relevant to asthma, such as airway epithelial cells." (PMID 29333270, 2017). "Studies have shown that genes on chromosome 1q32, including ADORA1 and PPFIA4 are associated with asthma risk, and ADORA1 may interact with sphingolipids to enhance airway inflammation." (PMID 36818476, 2022). "Thus, ADORA1 is thought to be involved in airway inflammation and remodeling in chronic lung diseases such as asthma and COPD." (PMID 35386996, 2021). "Similarly, using whole blood samples, polymorphisms of ADORA3 have been identified in patients with aspirin-induced urticaria, of ADORA1 and ADORA2A in aspirin-induced asthma, both in Korean population; ADA polymorphism have been observed in asthma patients from a Chinese Han population." (PMID 34068999, 2021). "The adenosine receptors (ADORA1, ADORA2A, ADORA2B, and ADORA3) have a promising therapeutic role in asthma and chronic obstructive pulmonary disease (COPD)." (PMID 35052792, 2022). "In particular, seven gene targets (HMGCR, ADORA1, IL6R, CD86, BCR, PIK3CD, and NOS1) are prioritized for asthma drug repurposing." (PMID 35052792, 2022). "Furthermore, there were apparent concordances between the association peaks for two loci (i.e., chromosome 19p13 with 1,2-dioleoyl-GPG, chromosome 1q32 with sphingomyelin [d17:1/16:0, d18:1/15:0, d16:1/17:0]) and genes that are known to be related to asthma (e.g., MUC16, ADORA1)." (PMID 36818476, 2022).